CHI3L1 (chitinase 3 like 1)
Diseases named in the same sentence as CHI3L1 in open-access papers (continued):
Sharing a sentence is not in itself a finding about the gene and the disease.
tumor (continued). "Functional studies revealed the pathological significance of CHI3L1 in driving both tumor progression and immunosuppressive TME." (PMID 34987649, 2022). "Anti‐Chi3L1 antibody‐treated tumor tissues promoted ARG1 and CD206 expression inhibition compared with vehicle‐treated tumor tissues but did not change iNOS and CD86 expression." (PMID 34861103, 2022). "Injecting 0.5 mg·mL−1 of anti‐Chi3L1 antibody twice a week for 4 weeks significantly reduced, tumor growth and size compared with Avastin treatment." (PMID 34861103, 2022). "Compared with the control group, the anti‐Chi3L1 antibody significantly reduced pSTAT6 expression in tumor and lung tissues." (PMID 34861103, 2022). "miR-26a/b-5p suppresses the expression of Chitinase 3 like 1 (YKL-40/CHI3L1), a driving force of tumor growth and metastasis, via targeting STAT3." (PMID 35406505, 2022). "PLG protein expression was significantly decreased in lung metastatic and tumor tissues of anti‐Chi3L1 antibody‐treated mice." (PMID 34861103, 2022). "Here, we show that humanized anti‐Chi3L1 antibody attenuated tumor growth and metastasis in vivo via STAT6‐dependent PLG signaling and M2 polarization inhibition." (PMID 34861103, 2022). "First, we selected representative genes that represented the unique epithelial cell type in each TET type based on scRNA-seq results and found that GNB3 and CHI3L1 were highly expressed in tumor cells of type 1 and type 3 TETs, respectively." (PMID 36115836, 2022). "Anti‐Chi3L1 antibody inhibits tumor growth and metastasis through STAT6‐induced M2 polarization inhibition and PLG expression." (PMID 34861103, 2022). "Anti‐Chi3L1 antibody‐treated mice had a greatly decreased tumor area and reduced number of tumor nodules." (PMID 34861103, 2022). "In conclusion, we showed that CHI3L1 is able to affect the tumor cell secretome, which in turn can regulate immune cell recruitment and blood vessel formation." (PMID 33920100, 2021). "CHI3L1 is a secreted glycoprotein that can facilitate tumor invasion and metastasis by upregulating the expression levels of matrix metalloproteinase (MMP) genes in various tumor cells." (PMID 34168643, 2021). "The CHI3L1 gene product is a glycoprotein that can be expressed and secreted by both tumor cells and immune cells." (PMID 33626234, 2021). "The CHI3L1–Erk correlation is in agreement with the previously proposed mechanisms involved in tumor biology." (PMID 33846436, 2021). "Future studies are needed to further delineate the mechanisms of CHI3L1-mediated macrophage recruitment and polarization in tumor tissues in order to provide novel insights for therapeutic intervention." (PMID 34612767, 2021). "We postulate that CHI3L1 modulates the tumor microenvironment by regulating the bioavailability of extracellular matrix-trapped cytokines or growth factors." (PMID 33920100, 2021). "In the present study, we showed that CHI3L1 can tune the tumor microenvironment by liberating HS-bound molecules such as CCL2 or VEGF-A." (PMID 33920100, 2021). "In other cancer models, genetic ablation of CHI3L1 in vivo reduced macrophage recruitment and increased effector T-cell infiltration in the tumor." (PMID 34532286, 2021). "The related angiogenesis and immune cell recruitment indicate that CHI3L1 is involved in endothelial cell activation and tumor inflammation." (PMID 33920100, 2021). "Future studies are needed to delineate the mechanisms of CHI3L1-mediated macrophage recruitment and polarization in tumor tissues." (PMID 34612767, 2021). "CHI3L1 can promote tumor progression by upregulation of pro‐inflammatory mediators, like CCL2, CXCL2, and MMP‐9." (PMID 33626234, 2021). "Together these studies suggest that CHI3L1 mediates a signaling loop between tumor cells and cells in the TME." (PMID 34832904, 2021). "Previously, high tumor burden and occurrence of metastasis in late-stage patients were mirrored by elevated CHI3L1 serum levels." (PMID 33920100, 2021).
tumor (continued). "ChI3L1 silencing in fibroblasts attenuated tumor growth, macrophage recruitment and its polarization to the M2 phenotype while enhancing T cell infiltration and the Th1 response." (PMID 34681633, 2021). "In fact, the role of CHI3L1 in eliciting angiogenesis has been extensively demonstrated in various tumor cells." (PMID 34349665, 2021). "Macrophages in tumor stroma have been shown to express CHi3L1 which is likely to stimulate tumor angiogenesis." (PMID 34820416, 2021). "The variables selected as significant after univariate analysis were the CHI3L1 and OPN expression levels in patient serum, tumor IDH1 mutational status, patient age, and malignancy grade." (PMID 33227903, 2020). "Concomitant with the results, we also observed the decreased tumor proliferation by Chi3L1 and PCNA immunostaining." (PMID 31929760, 2020). "Chi3L1 play a critical role as a Type 2 T helper (Th2) promoting cytokine that is present at high levels in the tumor microenvironment and in the serum of cancer patients." (PMID 32127023, 2020). "Chitinase 3 like 1 protein (Chi3L1) is expressed in several cancers, and a few evidences suggest that the secreted Chi3L1 contributes to tumor development." (PMID 32127023, 2020). "To date, there are no studies for the direct role of intracellular Chi3L1 on lung tumorigenesis, although higher expression and level of Chi3L1 in several cancer cells and tumor patient tissues have been reported." (PMID 32127023, 2020). "CHI3L1, a highly evolutionary conserved secreted protein, was recently shown to be involved in facilitating tumor progression and metastasis by triggering the MAPK and PI3K signaling pathways in macrophages." (PMID 32047513, 2019). "Extensive studies have suggested that monocytes/TAMs exert a pro-tumorigenic effect by the secretion of chitinase-3-like 1 (CHI3L1, YKL-40), interleukin-13 receptorα2 (IL-13Rα2) and then facilitating tumor cell invasion and migration." (PMID 30962764, 2019). "We showed an increased MAPK and AKT activation, which was observed in both, co-cultured conditions and CHI3L1 treatment of tumor cells." (PMID 31561550, 2019). "Our studies also suggest that Chi3l1 regulation of T cell response is a critical event in the pathogenesis of inflammatory and tissue remodeling and tumor growth and progression in which the expression of Chi3l1 is dysregulated." (PMID 29403003, 2018). "CHI3L1 upregulation occurred during GC development, and positively correlated with GC invasion depth, lymph node status, and tumor staging." (PMID 30165890, 2018). "Enzymatically inactive chitinase-like protein CHI3L1 drives inflammatory response and promotes tumor progression." (PMID 30165890, 2018). "To gain insight into the molecular mechanistic basis of the tumor facilitative effect of CHI3L1 in GC, we sought to identify CHI3L1 interacting partners." (PMID 30165890, 2018). "CHI3L1 is expressed by a vast array of cells including neutrophils, macrophages, fibroblasts, vascular smooth cells, endothelial cells, and tumor cells." (PMID 30165890, 2018). "To explore the role of CHI3L1 in tumor metastasis, we further utilized xenograft tumor models by subcutaneously injecting MGC803 cells transfected with lenti-shCHI3L1 or lenti-shControl into nude mice." (PMID 30165890, 2018). "Here, we added a novel regulatory function for intrinsic Chi3l1 in anti-tumor T cell immunity in pulmonary metastasis through functional regulation of Th1 cells and CTL activity." (PMID 29403003, 2018). "Here we utilized dNP2 peptide for effective siRNA delivery targeting Chi3l1 in tumor lung metastasis." (PMID 29403003, 2018). "The observed tumor-associated immune responses and the increased metastasis were associated with significantly induced local and systemic levels of MMP-9, VEGF, CHI3L1 and LCN2." (PMID 30111338, 2018). "Recently, accumulating evidence has demonstrated that CHI3L1 enhances the inflammatory response in the tumor microenvironment and promotes tumor progression." (PMID 30165890, 2018).
tumor (continued). "The tumor formed by the CHI3L1 knockdown cell (HepG2-shCHI3L1) grew significantly slower than the tumor formed by the control cells (p < 0.05)." (PMID 30301907, 2018). "The lower local and systemic levels of both biomarker proteins in RAW264.7 inoculated mice at 5 w p.i. further indicated the critical importance of crosstalk with tumor cells and anti-inflammatory signaling for the induction of CHI3L1 as well as LCN2." (PMID 30111338, 2018). "YKL-40/CHI3L1 are produced by a variety of cells, including neutrophils, monocytes, macrophages, chondrocytes, synovial cells, endothelial cells, and tumor cells." (PMID 29618952, 2018). "Accordingly, the tumor formed by the CHI3L1 overexpression cell (Bel7404-CHI3L1) grew significantly faster than the tumor formed by the control cells (p < 0.01)." (PMID 30301907, 2018). "Genetic ablation of Chitinase 3-like 1 (Chi3L1) in fibroblasts in vivo attenuated tumor growth, macrophage recruitment, and reprogramming to an M2-like phenotype, enhanced tumor infiltration by CD8+ and CD4+ T cells, and promoted a Th1 phenotype." (PMID 30380628, 2018). "In summary, our study demonstrated that CHI3L1 positively correlates with GC invasion depth, lymph node status, and tumor staging." (PMID 30165890, 2018). "It is noteworthy that CHI3L1 is expressed by a variety of cells including neutrophils, macrophages, fibroblasts, vascular smooth cells, endothelial cells, and tumor cells." (PMID 30165890, 2018). "Chitinase-3-like protein 1 (CHI3L1) is a mammalian glycoprotein and its expression is associated with tumor growth." (PMID 29535695, 2018). "Preliminary in vitro tests showed that co-cultures of 4T1 tumor cells with RAW264.7 macrophages secreted higher amounts of both CHI3L1 and LCN2 than either 4T1 or RAW264.7 mono-cultures." (PMID 30111338, 2018). "It is reported that CHI3L1-knockout tumor bearing mice has a significant reduction in tumor volume and metastasis compared with the wild-type controls." (PMID 30258444, 2018). "In conclusion, these studies define the many ways that tumor-induced Chi3l1 contributes to the generation of a metastasis permissive microenvironment and highlight the ability of RLH innate immunity to abrogate these responses." (PMID 27198666, 2016). "We found positive significant relationship between CHI3L1 mRNA level and high tumor malignancy (p < 0.001)." (PMID 27121858, 2016). "As a result studies were undertaken to define the mechanisms that Chi3l1 uses to foster tumor progression and metastasis." (PMID 27198666, 2016). "Additional investigation of the effects of Chi3l1 in the tumor microenvironment and the ways that RLH innate immunity can be manipulated to control metastasis is warranted." (PMID 27198666, 2016). "In these experiments we evaluated the expression of Chi3l1 in tumor inoculated WT mice treated with Poly(I:C) or vehicle control." (PMID 27198666, 2016). "CHI3L1 induces angiogenesis in vitro and in animal tumor models and is expected to promote evasion of CTCs from primary sites." (PMID 26425658, 2015). "CHI3L1, with proliferative effects, then promotes survival and expansion of both normal and tumor cells." (PMID 26431492, 2015). "CHI3L1-positive tumor cells, exhibiting altered regulation of VEGF and MMP9, decreased expression of cadherin and increased cell motility, display the combination of characteristics required to generate metastases as CTCs." (PMID 26425658, 2015). "Previous in vitro studies have suggested that CHI3L1 promotes proliferation in colon cancer cell lines and increases xenografted tumor load and angiogenesis." (PMID 26431492, 2015). "Results from SCLC CTC cultures suggest CHI3L1 as marker and important effector of tumor cell dissemination in the peripheral blood." (PMID 26425658, 2015). "Expression of endothelial and mesenchymal markers (ANGPT2, CHI3L1) indicated a stronger contribution of the micro-environment to the manifestation of the mesenchymal subtype than the tumor biology itself." (PMID 26673168, 2015).
tumor (continued). "CHI3L1-positive tumor cells armed with MMP9 and VEGF seem capable to pass the neighboring matrix and enter the bloodstream, possibly via newly formed microvessels." (PMID 26425658, 2015). "CHI3L1 has been linked to activation of the AKT pro-survival (anti-apoptotic) signaling pathway and enhances tumor survival in response to irradiation which is frequently applied prophylactically in SCLC." (PMID 26425658, 2015). "Our results demonstrating CHI3L1 as part of the secretome of ex vivo expanded SCLC CTCs point to these disseminated tumor cells as partial source of this protein directly produced in blood." (PMID 26425658, 2015). "In the tumor area, CHI3L1 expression on IEC was highly upregulated, which promotes cell proliferation (Ki67 positive staining) and suppresses cell death (Annexin V negative staining)." (PMID 26431492, 2015). "This treatment ultimately led to substantially reduced tumor growth and metastasis, indicating that chitin can impede Chi3L1 signaling." (PMID 25595947, 2015). "Together, these results indicate that the proliferative and pro-survival role of CHI3L1 particularly in IECs can promote tumor growth/expansion upon neoplastic transformation." (PMID 26431492, 2015). "In contrast, many reports have confirmed the tumor promoting and pro-metastatic functions of CHI3L1 in solid tumors." (PMID 26431492, 2015). "Chitinase 3-like 1 (CHI3L1/YKL-40, brown module) is a mesenchymal marker that promotes tumor angiogenesis and malignancy." (PMID 25940437, 2015). "KaLwRij macrophages had increased proliferation and increased Chi3l3 (1.80 fold), Chi3l1 (2.48 fold), and Cxcl2 (3.45 fold) expression, transcriptional markers for pro-tumor M2 macrophage polarization." (PMID 26020268, 2015). "The correlation of poor outcome and high CHI3L1 expression was also observed in patients whose residual tumor size was ≤ 1 cm after debulking surgery or chemotherapy with paclitaxel." (PMID 26452028, 2015). "In this review by Shao (2013), the roles and mode of action of YKL-40/chitinase-3-like-1 (CHI3L1) are described focusing on its angiogenic signature pertaining to tumor vascularization and development." (PMID 25071604, 2014). "The expression of CD44, CHI3L1 and ITGA6 are all associated with EMT, which were scarcely detected in the AOI as compared to their elevated expression at the tumor core." (PMID 25365423, 2014). "Loss of REL B led to lower levels of YKL-40 protein and decreased tumor size, and when overexpressed, it upregulated CHI3L1/YKL-40 mRNA." (PMID 24809021, 2014). "During inflammatory status, after Stat3C overexpression by doxycycline induction, the concentration of CHI3L1 was elevated in BALF of tumor-forming CCSP-rtTA/(tetO)7Stat3C bitransgenic mice (lane 5)." (PMID 23613996, 2013). "Western blot analysis of whole lungs from pre-metastatic tumor-bearers confirmed higher levels of pulmonary CHI3L1, and ELISA assays of total lung homogenates quantified this increase at 2 weeks." (PMID 24399973, 2013). "Transfection of HCT116 tumor cells with CHI3L1 enhances tumor growth, while in vivo treatment with anti-CHI3L1 neutralizing antibodies decreases angiogenesis." (PMID 24399973, 2013). "Production of CHI3L1 was increased more than 5-fold in pulmonary epithelial cells from tumor bearers, as measured by ELISA at 18 h post-plating." (PMID 24399973, 2013). "Regardless of lung tumor initiated from alveolar type II cells or myeloid cells, CHI3L1 was over-expressed in tumor cells of these MMP12 and Api6-induced spontaneous lung tumor mouse models." (PMID 23613996, 2013). "Intensity of CHI3L1 staining in alveolar macrophages similarly was greater in tumor bearers' macrophages, as determined by confocal microscopy." (PMID 24399973, 2013). "Even in the non-tumor-forming mice, CHI3L1 expression was highly induced in inflammatory cells of the lung." (PMID 23613996, 2013).
tumor (continued). "At 2 weeks post-inoculation, significantly higher levels of CHI3L1 were measured by ELISA in BALF samples from tumor bearers compared to control mice." (PMID 24399973, 2013). "Both tumor cells and inflammatory cells contribute to CHI3L1 protein elevation in BALF of doxycycline-treated CCSP-rtTA/(tetO)7Stat3C bitransgenic mice." (PMID 23613996, 2013). "CD11b+Ly6G+ cells from tumor bearers express CHI3L1 but these levels are lower compared to the levels observed in CD11b+Ly6C+ cells." (PMID 24399973, 2013). "Currently there is little known regarding mechanistic links between CHI3L1 expression by macrophages in the “pre-metatastic” lung, and tumor-related angiogenesis." (PMID 24399973, 2013). "Similar to what was observed in the interstitial macrophage population, there were higher than normal levels of CHI3L1 present in culture supernatants of alveolar macrophages from 2 week tumor-bearing mice." (PMID 24399973, 2013). "Immunohistochemical staining showed strong staining of CHI3L1 protein around tumor areas in these mouse models." (PMID 23613996, 2013). "We therefore examined the possibility that macrophage-derived CHI3L1 in the lung, upregulated by exposure to circulating CHI3L1 produced by tumor cells, “conditions” this organ to favor establishment of newly-arrived, metastasizing cancer cells." (PMID 24399973, 2013). "We demonstrate that CD11b+Ly6C+ populations in the lungs of tumor bearers produce high levels of CHI3L1." (PMID 24399973, 2013). "Similar to what was observed in total lung homogenates, CD11b+Ly6G+ cells from tumor bearers express CHI3L1 at lower levels compared to the CD11b+Ly6C+ cells." (PMID 24399973, 2013). "Since BALF was shown to contain elevated levels of CHI3L1, we determined which cell populations in the lavage contribute to the expression of CHI3L1 at 2 weeks post-tumor cell inoculation." (PMID 24399973, 2013). "Confocal images revealed higher intensity of CHI3L1 expression in CD68+interstitial macrophages from tumor bearers, relative to normal mice." (PMID 24399973, 2013). "The levels of CHI3L1 in the lungs are increased during pulmonary inflammation, and inflammation is known to contribute to tumor growth and metastasis." (PMID 24399973, 2013). "Since CHI3L1 protein concentration correlates very well with tumor occurrence in both regional inflammation and systemic inflammation-initiated spontaneous lung tumor mouse models, it is intriguing to determine if this observation can be repeated in humans." (PMID 23613996, 2013). "A similar result was also observed in the serum of Api6-induced tumor mice, in which the average CHI3L1 concentration was 3 times higher in tumor mice than that of doxycycline-untreated control mice." (PMID 23613996, 2013). "In vivo treatment with chitin microparticles resulted in decreased CHI3L1 expression in BALF collected form 5 week tumor-bearers." (PMID 24399973, 2013). "We and others have recently shown that a glycoprotein known as chitinase-3-like-1 protein is produced by macrophages from tumor-bearing hosts." (PMID 24399973, 2013). "The secreted interleukin-like Gro-alpha oncogene (CXCL1) and matrix-metalloproteinase 3 (MMP3) promote tumor initiation and growth, while chitinase 3 like-1 (CHI3L1) can protect cancer or/and stromal cells against apoptosis." (PMID 23155391, 2012). "Immunostaining with anti-CHI3L1 antibodies revealed CHI3L1-positive cells both in tumor tissue and in the border of tumor (an invasion zone)." (PMID 23675241, 2011). "Tumor formation by 293 stably expressing CHI3L1 in rat brains strongly suggests that this gene is involved in oncogenesis and can be used as a target for anticancer drug development after understanding the mechanisms of CHI3L1 oncogenicity." (PMID 23675241, 2011). "In necrotic cases, CHI3L1 demonstrated a distinct staining pattern in tumour cells adjacent to the areas of necrosis." (PMID 18781180, 2008).